TGFB1 (transforming growth factor beta 1)
Diseases named in the same sentence as TGFB1 in open-access papers (continued):
Sharing a sentence is not in itself a finding about the gene and the disease.
cancer (continued). "A key factor responsible for the stimulation of EMT in cancer cells is TGFB1; thus, we determined its secretion using the ELISA technique." (PMID 40141419, 2025). "The upstream activation of SNAIL in ARMS is closely linked to the overexpression of transforming growth factor beta 1 (TGF-β1), a pleiotropic cytokine with known roles in cancer progression and immune modulation." (PMID 40508013, 2025). "Both substances contribute to stimulate CAF endoglin expression and therefore negatively modulate the TGFβ1/SMAD2/3 pathway in cancer cells by decreasing extracellular TGFβ1 levels." (PMID 40384860, 2025). "As TGFβ1 also plays a central role in cancer, it can be expected that asporin would be affected in these diseases too." (PMID 41463344, 2025). "TGFβ and G9a contribute to fibrosis and cancer, and some studies have shown that TGFβ1 promotes the expression of G9a in rat kidney epithelial cells and human peritoneal mesothelial cells." (PMID 40661662, 2025). "ROS, IL-10 and TGFB1 produced by MDSCs negatively regulates CD8+ T cells activity against cancer cells." (PMID 39981232, 2025). "According to multiple pan-cancer analyses, SHCBP1 expression is also positively associated with TMB, MSI, immune cell infiltration values, and the expression of immunosuppression-related genes, such as TGFBR1, PD-L1, and TGFB1 in various cancers." (PMID 41009347, 2025). "We observed that decreased TGFB1 expression in luminal A cancer and its overexpression in HER2-negative luminal B cancer were associated with worse OS." (PMID 41465262, 2025). "For example, Snail (an EMT-inducing transcription factor) and the growth factor TGFβ1 were previously reported to be regulated by METTL3 required for the development of cancers." (PMID 40612868, 2025). "To explore these issues, we used various public data platforms such as TCGA database and GEO database to systematically discuss the role of TGFβ1 in cancer prognosis, immune infiltration and polarization of subtypes of macrophages." (PMID 39991579, 2025). "HCC cells in which JUNB expression was increased by fibroblast-derived TGFb1 were transformed into mesenchymal cancer cells, with potential to metastasize to the lungs." (PMID 40253402, 2025). "In a clinical study conducted by and coworkers involving 198 gastric cancer patients who underwent surgery, the group with lipopolysaccharide positivity exhibited higher levels of cancer stromal TGFB1 expression and increased PD-L1 expression in cancer cells." (PMID 40666174, 2025). "BCAM-induced proteins, previously reported to drive EMT and associated processes such as cell migration in various cancers, include AREG, CXCL1, CXCL10, EDN1, FGF2, TGFβ1 and VEGFB." (PMID 40082910, 2025). "TGFB1 from cancer cells activated CAFs to produce THBS2 through the p-Smad2/3 pathway, suggesting an important role for TGFB association with THBS2 in cancer progression." (PMID 41373732, 2025). "Clinically, plasma Tgfβ1 levels correlate with the MO-MDSC/PMN-MDSC ratio across cancer types, highlighting its biomarker potential." (PMID 41360769, 2025). "Here, we investigated the metabolic activity of PANC-1, SW620, and MCF-7 cancer cells following treatment with TGFβ-1, IL-6, and HGF at predetermined concentrations." (PMID 40227834, 2025). "Our study places miR-9 in the same functional context with G4s and promoter-enhancer interactions during 3D genome organization and transcriptional activation induced by TGFB1 signaling, a critical signaling pathway in cancer and fibrosis." (PMID 39706840, 2024). "We found that in MCF7 cells, TGFB1 acts as an inhibitor of proliferation and inducer of cell death (possibly apoptosis), which suggests that these cells originated from early-stage cancer." (PMID 39468555, 2024).
cancer (continued). "TGFβ-mediated EMT is only observed in epithelial plastic cancer cells, even though full epithelial cancer cells from WD-SCCs also exhibit a functional TGFβ signaling transduction upon TGFβ1 treatment." (PMID 39075581, 2024). "As with CAFs and transitional fibroblasts, TGFβ1 and 3 were likewise highlighted as important paracrine regulators of cancer cells." (PMID 39485038, 2024). "TGFB1 was overexpressed in GC cells and participated in cancer progression by inducing cell proliferation, metastasis, glycolysis, angiogenesis, and depressing apoptosis." (PMID 38402299, 2024). "- TGFB1 increases in cancer and normal tissues as individuals age.- TGF-β elicits senescence in fibroblasts, bronchial epithelial cells, and neoplastic cells." (PMID 38590525, 2024). "Recent research has demonstrated that TGFβ1 plays a role in immune suppression across various cancers." (PMID 39518137, 2024). "Glycoprotein-A repetitions predominant (GARP) is a cell surface docking receptor for activating latent TGFβ1, TGFβ2, and TGFβ3, with its expression restricted predominantly to effector Treg and cancer cells." (PMID 38085441, 2024). "FOS showed positive correlations with critical genes such as VEGFA and TGFB1, indicating its possible role in immune regulation and cancer progression." (PMID 39063239, 2024). "TGFβ1 and estradiol (E2) are identified as the growth signals specifically needed by the cancer type (see Method 7), and f2x and f3x are their age-dependent distributions, respectively." (PMID 39796131, 2024). "In contrast, EpCAMhigh and EpCAMlow cancer cells gave rise to a higher percentage of mesenchymal cancer cells upon TGFβ1 treatment, indicating that only epithelial plastic cancer cells respond to TME-derived signals to promote cSCC progression." (PMID 39075581, 2024). "Platelets act to initiate an invasive mesenchymal phenotype through the liberation of TGFβ1 and ATP from granules, thereby inducing endothelial junction modification and enhancing transendothelial migration of cancer cells." (PMID 38397421, 2024). "MCF10A (noncancerous, originating from fibrotic breast tissue) and MCF7 (cancer, estrogen receptor-positive) breast epithelial cells were treated with TGFB1 directly or through conditioned media from stimulated cells." (PMID 39468555, 2024). "Previous studies have indicated that targeting immunosuppression by TGFβ1 is a viable strategy for cancer immunotherapy." (PMID 38919521, 2024). "Numerous studies identified TGFβ1 as a key cytokine associated with the Epithelial-Mesenchymal Transition (EMT) program, which not only enables cancer cells to metastasize but also reduces their sensitivity to chemotherapeutic agents." (PMID 38558874, 2024). "By identifying TGFβ1 in this preventive mechanism against cancer, this study questions the suitability of cancer immunotherapy strategies that are based on systemic TGFβ1 targeting to restore efficient T cell cytotoxic functions against cancer cells." (PMID 39060651, 2024). "CAFs facilitate cancer immune evasion by forming a physical barrier to prevent immune cells from entering tumors and by producing immune regulatory molecules, such as TGFβ1 and PD-L1, to suppress the antitumor activity of immune cells." (PMID 39218981, 2024). "Thrombin, as a core member of coagulation, can stimulate platelet release of TGFβ1 which can accelerate cancer cell proliferation and metastasis." (PMID 39440053, 2024). "By applying the method outlined in Method 7, we have predicted BMP6, TGFα, and TGFβ1 as the growth signals specifically needed by the cancer type." (PMID 39796131, 2024). "TGFB1 (transforming growth factor beta 1) is a potent cytokine playing a driving role in development, fibrosis, and cancer." (PMID 36983741, 2023). "Our results provide novel insights into the functional role of TGFB1 in hematological malignancies and the potential as cancer immunotherapy targets." (PMID 37925591, 2023).
cancer (continued). "TGFB1 showed a hematologic-tissue-specific expression pattern both across normal tissues and cancer types." (PMID 37925591, 2023). "This cluster included genes well known to mediate CAF-TAM interactions in cancer, such as Tgfb1, Csf1, and Ccl232." (PMID 37726308, 2023). "In this work, we show that nanoparticle-mediated TRPV1 blockade selectively suppresses stressful HSP70 and TGFβ1 via effective modulation of heat shock factor 1 (HSF1) for augmented thermo-immunotherapy against highly malignant tumors." (PMID 37120615, 2023). "According to the findings by Webber, TGFβ1, which is an element of exosomes that are released by cancer cells, is essential for the advancement of malignancy." (PMID 38202898, 2023). "In detail, activated transcription factors, such as FOXO1, HIF1A, STAT3, and JUN, regulate the expression of TGFB1, TGFB3, IL1B, and TNF, promoting cancer hallmarks associated with these ligands." (PMID 37370765, 2023). "KLF4 has been known to activate the mesenchymal program in cancer stem cells through the increased activity of the TGFB1/SMAD signaling." (PMID 38129585, 2023). "We found that IFNA1 and IFNL1 gene transcripts resulted negligibly expressed across the pan-cancer dataset when compared to other immunosuppressive and pro-inflammatory cytokines such as TGFB1/2, PTGES2, IL1A, IL1B, IL6 and CSF1." (PMID 38239354, 2023). "Emerging evidence suggests that Schwann cells promote cancer cell metastasis by secreting C-X-C Motif Chemokine Ligand 5 (CXCL5), Interleukin 6 (IL-6), and Transforming Growth Factor Beta 1 (TGF-β), or by direct cancer cell contact." (PMID 37524695, 2023). "Overall, these data confirm the potential ability of TGFB1 in predicting immunotherapy response across cancer types." (PMID 37925591, 2023). "Univariable cox regression analysis was used to assess the prognostic impact of TGFB1 in each dataset, followed by a meta-analysis of cox regression values (p values and HRs) inside each cancer type." (PMID 37925591, 2023). "After the treatment of ARNIPL to 3D cancer spheroids, ARV-825 induced the BRD4 depletion-associated down-regulation of c-Myc, and nintedanib inhibited the transforming growth factor beta 1 (TGF-β1), resulting in synergistic antitumor efficacy." (PMID 36839734, 2023). "In both pre-cachexia and cachexia stages, elevated expression of the canonical signaling pathway of TGFβ1 has been observed in the plasma of cancer patients." (PMID 37701438, 2023). "Since TGFB1 and IL6ST are the two modules with the highest degree of molecular connectivity, we compared the cancer types with which each of these modules is associated." (PMID 38054018, 2023). "Overall, the transcriptome and staining results demonstrated that VEGFA and TGFβ1 signalings, two hallmarks of full-blown cancer, have essential roles in OSCC initiation, with a spatial-switching regulation of VEGFA surrounding the DN stages." (PMID 36914617, 2023). "EndMT is known to be initiated by TGFB1, and is exacerbated by TNF in cancer-associated fibroblasts; therefore, it is possible that the increases in content of TNF and TGFB1 during luteal regression can contribute to EndMT." (PMID 37841308, 2023). "In support of this finding, hypoxia (which is known to promote cancer progression, angiogenesis and metastasis) changes the levels of m6A writers, erasers and readers, resulting in a decrease in m6A levels and an increase in TGFβ1 expression in cancer cells." (PMID 38053093, 2023). "This expression profile of TGFβ1 is consistent with the defined role of TGFβ1 in the initiation of EMT-related progression in other cancers." (PMID 37174052, 2023). "While extensive research has been conducted on the role of TGFβ1 in other wasting conditions such as muscle dystrophy, the contribution of TGFβ2 and TGFβ3 to cancer cachexia remains unexplored." (PMID 37701438, 2023).
cancer (continued). "Based on the differential expression genes (DEGs) between the high- and low- TGFB1 subgroups, we performed GSEA analysis across blood cancer types to evaluate the TGFB1-associated cancer hallmarks." (PMID 37925591, 2023). "EMT inducer such as transforming growth factor β1 (TGFβ1) has been shown to induce a variety of complex signalling pathways in cancer cells." (PMID 37174052, 2023). "In pancreatic cancer, membrane-bound TGFβ1 on cancer-expanded myeloid-derived suppressor cells (MDSC) was found to induce NK cell dysfunction through diminished NKG2D expression and impaired NK cytotoxicity." (PMID 36980629, 2023). "As is known, TGFβ1 activation through the suppression of T cells’ anticancer function decreases the immune surveillance function against cancer generation." (PMID 37175975, 2023). "Remarkably, higher TGFB1 expression negatively correlated with patient outcomes in all three types of cancers by performing meta-analyses." (PMID 37925591, 2023). "Increased cellular uptake of folate-HSA-MTX and TGF antibody on nanoparticles scavenged extracellular TGFβ1 of cancer cells, reducing cell migration." (PMID 37048731, 2023). "Consistent with the cancer hallmark analysis, TNF (TNFSF13B), TGFB1, and TGFB3 played important roles in the mesenchymal microenvironment crosstalk." (PMID 37370765, 2023). "We subsequently performed IHC staining to validate the expression of VIM and TGFB1 in cSCC in a clinical cohort that comprised 16 patients with cancer progression events, from primary tumors to cSCCs with single or multiple recurrences." (PMID 36438481, 2022). "Transforming growth factor beta (TGFB1), which plays pleiotropic roles in cancer progression, was found to be upregulated in lung squamous carcinoma." (PMID 35433477, 2022). "TGFβ defines three subtypes (TGFβ1, TGFβ2, and TGFβ3), of which TGFβ is highly expressed in many cancers, especially those showing high dissemination potential." (PMID 36119489, 2022). "We found that there was a trend of overexpression of genes in the TGF-β signaling pathway of cancer cells, which suggested potential pathway activation of TGFB1-ENG at the single-cell level." (PMID 36249427, 2022). "RCC tissues that successfully generated organoids highly expressed genes associated with stemness (WNT6/11, FZD8/9 and JAG2), cell matrix (MMP2, COL1A1), fatty metabolism (ACOT2, LIPE) and cancer development (TGFB1, SMAD6/7, EGF and FGF1)." (PMID 35802820, 2022). "Inhibition of the Transforming Growth Factor-beta-1 (TGF-β1) pathway has been shown to block the EMT process in cancer cells in vitro, and, consequently, to restore the cytotoxic activity of HER2-specific CAR-T cells." (PMID 35565264, 2022). "A biological network predicted a major activation of growth factor, Transforming growth factor beta (TGFB1) is an important member of the transforming growth factor beta (TGF-β) family and plays pleiotropic roles in cancer progression." (PMID 35433477, 2022). "Recently TGFB1 has been shown to be released by SA, which has many known effects in cancer and the tumor microenvironment." (PMID 36601581, 2022). "Since TGFβ1 has been reported to induce EMT in cancer cells, this cytokine was also studied in spheroids on Day 8, and it was found that TGFβ1 mRNA was significantly upregulated in gRNA2 cells compared to control." (PMID 36585738, 2022). "In this study, we found that the JAG1 level on PDAC organoids was increased by ductal differentiation, and JAG1 consequently increased the WNT5B and TGFb1 levels by stimulating ECs, leading to cancer cell plasticity and anti-inflammatory microenvironment." (PMID 35673567, 2022). "Accordingly, the secreted TSP1 by cancer cells augmented the expression and activation of TGFβ1 in the hepatocytes in their neighbouring hepatocytes." (PMID 35267627, 2022). "The involvement of TGFβ-1 in signaling for cancer occurrence and development is illustrated in several studies." (PMID 35419691, 2022).
cancer (continued). "TGFβ defines three subtypes (TGFβ1, TGFβ2 and TGFβ3), among which TGFβ2 is highly expressed in many cancers, especially those tumors that show high transmission potential (Massagué, 1998)." (PMID 35620459, 2022). "TEV enriched in TGFβ1 were described in gastric, bladder, head and neck cancer, mesothelioma, breast, prostate and other cancers." (PMID 36011012, 2022). "TGFβ1, an isoform of TGFβ, has been reported to have bi-directional roles in cancer progression as well as exert suppressive and pleiotropic effects on the immune system, including the regulation of T cells, natural killer cells, and macrophages." (PMID 35311069, 2022). "It has also been documented that overexpression of the TGFB1 reduces the immune response against cancer cells, which promotes the process of carcinogenesis." (PMID 35798776, 2022). "Eventually vascular sprouting activates TGFβ1, that in turn stimulates the resumption of proliferation by these dormant cancer cells." (PMID 35321751, 2022). "Essentially, the addition of anti-TGFβ1 neutralizing antibodies before co-culture caused reversal of invasion abilities of MDA-MB-231 and MCF7 cancer cells." (PMID 35955525, 2022). "Sustained low-dose TGFβ1 exposure can promote epithelial-mesenchymal transition (EMT) of cancer cells 28-30." (PMID 35414781, 2022). "Cancer cell-derived TGFβ1 induces de novo expression of TN-W in the stromal cells, providing an important component for the metastatic niche." (PMID 35785162, 2022). "On the other hand, in later stages of cancer development, TGFβ1 increases the migratory and invasive capacity of cancer cells by inducing EMT." (PMID 34983624, 2022). "Cell invasion associated with cancer progression requires EMT, and the activation of RHOA via TGFβ1 signaling induces GC cell migration via EMT." (PMID 35804944, 2022). "TGFβ1 secreted by the TME interacts with TGFβ receptor 1 expressed on cancer cells, and this ligand-receptor pair is dramatically upregulated in left-sided CRC." (PMID 34793335, 2022). "In late-stage cancer, cells seem to become resistant to its anti-mitotic effects and TGFB1 was instead observed to stimulate EMT by upregulating mesenchymal markers (e.g., VIM, CDH2) and downregulating epithelial markers (e.g., CDH1)." (PMID 35565214, 2022). "The TGFβ1-pSMAD2/3 pathway is one of the most important pathological pathways involved in the development of malignant tumours." (PMID 35186724, 2022). "WNT5B and TGFB1 expressions were increased in ECs through the interaction with JAG1 on cancer cells." (PMID 35673567, 2022). "It is important to highlight that the pathological significance of the observed effect of TGFβ-1 treatment on PM localization of different Ras isoforms in cancer progression remains yet to be explored." (PMID 35931724, 2022). "Last but not least, it is important to highlight that the pathological relevance of the observed effect of TGFβ-1 treatment on PM localization of different Ras isoforms for cancer progression is currently unclear and should be the subject of further studies." (PMID 35931724, 2022). "In premalignant stages of cancer, TGFβ1 acts as a tumor suppressor by inhibiting proliferation and inducing apoptosis in epithelial cells." (PMID 34983624, 2022). "In summary, the ectopic expression of PDX1 reduces the migration potential of cancer cells at early stages, particularly by increasing the adhesive properties of cells and reducing the sensitivity of cells to TGFβ1-induced EMT." (PMID 34503200, 2021). "According to previous studies, cancer cells secrete diverse factors, such as sonic hedgehog, TGFβ1, VEGF, CTGF, and PDGF, which promote PSC activation." (PMID 34849465, 2021). "Cancer cells secrete TGFβ1 and chemokines, which activate resident fibroblasts and induce their differentiation into CAFs." (PMID 34950592, 2021).